PRL (prolactin)
Diseases named in the same sentence as PRL in open-access papers (continued):
Sharing a sentence is not in itself a finding about the gene and the disease.
Obesity (continued). "Mean PRL levels were not significantly different between individuals with a normal BMI (<25 kg/m2) compared to those overweight and with obesity (BMI ≥ 25 kg/m2); however, PRL levels were significantly suppressed after food intake only in subjects with a normal BMI." (PMID 39338159, 2024). "Our findings suggest a minor role of systemic PRL in pathogenesis of RA and periodontitis as serum levels could be influenced by a variety of factors like obesity and plasma insulin levels." (PMID 36717425, 2023). "Paradoxically, the opposite is observed, with reduced PRL levels observed in some cases of obesity and metabolic disease, suggesting a hypothalamic–pituitary dysfunction might be to blame for the alterations in PRL levels." (PMID 38004264, 2023). "Serum prolactin level should be screened in obese patients, especially those with severe obesity." (PMID 38093965, 2023). "Obesity and IR are metabolic stimuli that could stimulate homeorhetic response and elevate PRL levels to a specific range that promotes metabolic homeostasis." (PMID 38004264, 2023). "Indeed, subjects having MHO have increased circulating PRL levels as compared to those with metabolically unhealthy obesity (MUHO)." (PMID 36213259, 2022). "In obese humans, PRL levels were increased in metabolically healthy obesity." (PMID 36704037, 2022). "Since obesity is associated with higher NAFLD incidence, whether prolactin has hepatoprotective roles in NAFLD received mass attention." (PMID 35860276, 2022). "The authors suggested that increased circulating PRL might be a compensatory response for favoring energy metabolism during obesity." (PMID 36704037, 2022). "Even though in transgenic mice lacking prolactin no profound metabolic phenotype was demonstrated, mice with Prlr deficiency showed a worsening in the induction of obesity or streptozotocin evoked diabetes." (PMID 35757410, 2022). "On the other hand, we found a strong inhibitory effect of prolactin and not HFD on Lpl and adiponectin expression levels in scWAT, which may suggest an additional mechanism participating specifically in prolactin-induced obesity." (PMID 35757410, 2022). "Moreover, the detrimental effect of PRL excess on BMI has also been demonstrated to be a common finding in young patients with prolactinoma onset during childhood since a prevalence of obesity of about 35% has been reported at diagnosis at this age." (PMID 36237192, 2022). "Moreover, serum prolactin levels were also negatively influenced by smoking and obesity, whereas they were positively influenced by a sedentary lifestyle." (PMID 36303626, 2022). "An unexplored but promising therapy is the clinical use of prolactin since administration with prolactin or prolactin-releasing peptide evidently improves steatosis in mice obesity models, and ablation of prolactin receptor increases hepatic triglyceride accumulation." (PMID 35860276, 2022). "Although PRL release is affected by obesity, the mechanism and consequences of decreased PRL release due to obesity are still largely unknown." (PMID 32477263, 2020). "Individual risk factors for poor physical health included high levels of obesity upon admission, subsequent weight gain, high levels of self-reported sedentary behaviour, increased smoking rates and some evidence of increased levels of lipids and prolactin." (PMID 31679539, 2020). "Our results support the view that obesity decreases PRL release and lows serum PRL." (PMID 32477263, 2020). "The relationship between PRL and obesity is unclear and remains to be elucidated." (PMID 30396878, 2019). "However, a study comparing adults with overweight/obesity, found hormonal differences (e.g., amylin, prolactin, thyroid stimulating hormone) between those who met criteria for food addiction and those who did not." (PMID 29649120, 2018).
Obesity (continued). "Obesity in the elderly is also related to changes the hormonal environment, which includes a decline of growth hormone and testosterone, decreased responsiveness to thyroid hormone and leptin, and increased prolactin and cortisol levels." (PMID 29244825, 2017). "So far, our findings indicate that obesity leads to prolactin resistance during lactation." (PMID 26926925, 2016). "Nine loci have been associated with extreme obesity at the genome-wide level, five of them influencing BMI / waist circumference as well as risk for extreme obesity (FTO, MC4R, TMEM18, MSRA, NPC1), four loci being more specific of genetic risk for extreme obesity (MAF, PTER, PRL, SDCCAG8)." (PMID 22043164, 2011). "Other obesity susceptibility variants in/near MAF, NPC1, PRL, and PTER have been identified in other GWA studies of early-onset and severe obesity, and putative associations with early life weight gain may be more expected with those variants." (PMID 20520848, 2010). "In addition, obesity alters the 24 hour spontaneous release of PRL with a generalised dampening of release." (PMID 20182553, 2010). "Notably, majority of the A12 neurons, including the TH/GABA subpopulation are responsive to prolactin, hence prolactin activation of this subpopulation of A12 neurons could account for hyperprolactinemic link to obesity." (PMID 39919032, 2025). "Moreover, reduced prolactin activity has been observed in lactating obese rodents and in women with obesity, which may be responsible for reduced lactogenesis and synthesis of milk components, as well as increased lipogenesis and lipid stored in adipocytes." (PMID 39275171, 2024). "Difference in prolactin response in obesity may have an effect on breastfeeding." (PMID 39463500, 2024). "PRL may promote the expansion of adipose tissue and obesity indirectly by increasing appetite." (PMID 37626804, 2023). "Therefore, preventing obesity in gestating sows through high DF intake may increase prolactin concentration in serum." (PMID 37641826, 2023). "However, this is certainly an area worthy of future study; some recent work, outside the scope of this review, has suggested lower baseline maternal PRL levels and lower PRL responses to suckling in women with obesity, a condition that often accompanies these conditions." (PMID 36769162, 2023). "In this context, prolactin may represent an additional player in the development of obesity, which is multifactorial in origin, and therefore the interrelation of genetic, endocrine, behavioral and environmental factors deserves greater attention in the search of strategies to combat overweight." (PMID 35757410, 2022). "It is postulated that women with obesity may have elevated baseline progesterone levels which prevent the sharp decline in progesterone after delivery of the placenta that triggers lactogenesis, and that obesity alters the prolactin response to neonatal suckling in these mothers." (PMID 35928678, 2022). "In addition, it is important to notice that different levels of PRL might have different and even opposite effects on metabolic disorders, such as obesity, diabetes, and metabolic syndrome." (PMID 35222274, 2022). "There is a report suggesting that serum prolactin may be lower in children with obesity." (PMID 28529200, 2017). "Therefore, diet-induced obesity led to prolactin resistance in the mammary tissue and hypothalamus." (PMID 26926925, 2016). "However, to the best of our knowledge, prolactin resistance has not previously been associated with obesity." (PMID 26926925, 2016). "Therefore, in an attempt to uncover the mechanisms involved in obesity-induced impaired lactation, we investigated whether obese females present normal responsiveness to prolactin." (PMID 26926925, 2016).
Obesity (continued). "Other obesity associated factors, such as cortisol dysregulation, prolactin signaling, and circadian or sleep disturbances, were not captured in this study and may therefore represent unaccounted contributors to the observed differences in milk HA concentrations." (PMID 41305610, 2025). "We analysed PRL, hPL and GH2 concentrations with respect to maternal age and obesity in SCOPE to determine if hormone concentrations are different in older women or those with obesity, or with a combination of the two in healthy pregnancy." (PMID 37049394, 2023). "Patients with obesity and high PRL (HP) levels displayed reduced blood glucose, total and LDL cholesterol, triglyceride, and TNFα levels than patients with obesity and normal PRL (NP) levels." (PMID 36213259, 2022). "Significant decrements in the expression of Ucp1 and Pgc1a mRNA as well as UCP1 protein levels induced by prolactin but not by HFD, indicate that prolactin, independently of the diet or obesity, may predispose to the development of an obese phenotype by lowering the thermogenic capacity of BAT." (PMID 35757410, 2022). "In PCOS OUH, age, obesity (BMI, waist), BP (systolic and diastolic), lipid status (LDL, cholesterol, TG), prolactin, blood glucose (fasting, 2 h), insulin (fasting, HOMA-ir) were significant predictors for development of CVD." (PMID 29519249, 2018). "The relative resistance to HFD-induced obesity was accompanied by a more favorable carbohydrate homeostatic profile in PRLR−/− mice, consistent with the major implication of PRL signaling in energy balance." (PMID 24667351, 2014). "The positive effect of leptin inhibition on trabecular bone fraction and weight gain in diet-induced obesity resistant PRLR−/− mice, suggests that leptin and PRL signaling pathways are acting separately from each other." (PMID 24667351, 2014). "Patients without diabetes and hypertension exhibited significantly higher prolactin levels, but gender and obesity did not considerably impact prolactin values." (PMID 40650124, 2025). "We conclude that sulpiride reduces obesity-induced hyperglycemia by mechanisms that are independent of prolactin/prolactin receptor activity." (PMID 38635745, 2024). "The potential role of PRL in the context of obesity and metabolic syndrome becomes apparent from the lack of significant weight loss observed upon treating non-functioning adenomas, unlike it has been observed in patients with prolactinomas." (PMID 38510701, 2024). "The enrichment analysis revealed that these phenolics may combat obesity through PI3K-Akt signaling and MAPK, prolactin, and cAMP signaling pathways." (PMID 38929640, 2024). "Another condition worth of notice is pregnancy in patients with obesity, since cases of delayed or absent lactation have been reported, possibly due to altered feedback loops related to PRL secretion stimulated by infant suckling." (PMID 39172174, 2024). "High levels of placental lactogens and prolactin during pregnancy, as well as the adipokine complex in obesity without diabetes, are important factors that affect increased islet cell mass and β-cell proliferation." (PMID 39045459, 2024). "However, this was an expected result as some studies excluded people with abnormal BMI, obesity, prediabetes, diabetes, high TSH, or high prolactin." (PMID 37624626, 2023). "Despite the high prevalence of obesity and overweight in a cohort of patients with prolactinoma, six months of DA treatment and normal PRL levels did not lead to a significant difference in BMI." (PMID 36704037, 2022). "The observed reduction in the levels of expression of the typical markers of BAT, exclusively in hyperprolactinemic non obese and not in HFD fed mice point to an action of prolactin independently of food intake driven-obesity." (PMID 35757410, 2022). "Obesity was also not assessed among children in our study cohort and serum prolactin levels were not adjusted for childhood obesity." (PMID 28529200, 2017).
Obesity (continued). "Especially interesting and promising target molecules for obesity-derived implications in placenta could be CCL2, PRL, MMP12, TAC3, PRG2 and IGFBP1 that were the most dysregulated genes among our study group." (PMID 28125591, 2017). "Moreover, subjects with a normal BMI showed significant suppression in prolactin levels after food intake, while those overweight and with obesity did not." (PMID 39338159, 2024). "Mean PRL levels were not significantly different between individuals with a normal BMI (<25 kg/m2) in the fasting, early, and late postprandial states compared to those overweight and with obesity (BMI ≥ 25 kg/m2)." (PMID 39338159, 2024). "In women, there are no studies relating prolactin resistance to obesity; this is a hypothesis that deserves to be further studied." (PMID 39770967, 2024). "Within normal concentrations, PRL is not considered as a major factor in the occurrence of obesity." (PMID 36993818, 2023). "As a proof of concept, PRL treatment in mice and rats with streptozotocin (STZ)-induced diabetes or diet-induced obesity improves their metabolic profile, whereas PRLR null mice with STZ-induced diabetes or diet-induced obesity show a more severe disease phenotype." (PMID 36213259, 2022). "A study investigated the metabolism between obesity with or without increased PRL." (PMID 36313749, 2022). "Therefore, severe high prolactin levels may target BAT function, and furthermore represent an adjuvant player in the development of obesity induced by high fat diets." (PMID 35757410, 2022). "The protective role of PRL in diabetes is further suggested by the facts that the circulating levels of PRL are reduced in rats with streptozotocin (STZ)-induced diabetes and diet-induced obesity, and low circulating PRL levels are deleterious for glucose homeostasis." (PMID 33746901, 2021). "Therefore, diet-induced obesity recapitulated the food intake phenotype of brain-specific STAT5 deletion, supporting the hypothesis of impaired prolactin signaling in the brain of HFD animals." (PMID 26926925, 2016). "Interestingly, obesity, which is a hyperleptinemic condition, has negative effects on some biological functions regulated by prolactin." (PMID 26926925, 2016). "Findings from our current study indicate that the combined abnormality of TSH and prolactin might be one of the hormonal characteristics in obesity with food addiction rather than in general obesity." (PMID 25558907, 2014). "Thus, there does not seem to be a significant role of prolactin in the pathophysiology of obesity." (PMID 35860276, 2022). "We analyzed the interaction of diet-induced obesity with the lack of SST and CORT on the production and secretion of key pituitary hormones by determining GH, IGF and PRL levels at sacrifice." (PMID 27901064, 2016).
depression (116 papers, 2005 to 2026). "Downregulation of the PRL gene has been associated with major depression in postmortem human brains and chronic stress in mice." (PMID 40473930, 2025). "In the context of comorbid depression and psychosis, serum lipids and prolactin have also been found to be associated with affective symptoms." (PMID 40736066, 2025). "Testosterone (p0.024), FP Follicle Stimulating Hormone (FSH) (p0.009), FP Estradiol (p0.006), LP FSH (p0.031), LP Progesterone (p0.023), and LP Prolactin (p0.000) were associated with depression." (PMID 38711940, 2024). "In a study by Groër71, high depression scores were inversely associated with lower serum PRL concentrations." (PMID 39548101, 2024). "PRL deficient patients with panhypopituitarism had higher depression scores compared to the controls, lower sexual function scores in males." (PMID 38700812, 2024). "Of all sex steroid hormones that are associated with epilepsy, only PRL and testosterone predicted depression in PWE." (PMID 38711940, 2024). "An increase in prolactin level is associated with a low level of dopamine and, consequently, higher signs and symptoms of depression." (PMID 38711940, 2024). "FP FSH, FP estradiol, FP PRL, LP progesterone, LP estradiol, LP PRL, and testosterone levels are associated with depression in patients with epilepsy." (PMID 38711940, 2024). "Of note, we also reported DRD2 and PRL-variants conferring risk for type 2 diabetes and depression, which can both coexist with PCOS." (PMID 37563671, 2023). "PRELP (Prolargin) related to neural regulation, decreased prolactin is associated with depression and insomnia." (PMID 32249904, 2020). "The present study provides evidence supporting the association between PNN density in the PrL and depression." (PMID 32116542, 2020). "A link between the prolactin response to a serotonergic challenge and affective symptoms, such as depression and guilt, has been reported in one study; given this, it is logical to examine the association between prolactin levels and suicide." (PMID 24800074, 2014). "When patients were divided into 2 groups according to PRL deficiency, PRL deficient patients with panhypopituitarism had higher depression scores compared to the control group, but PRL sufficient patients had similar depression scores compared to the control group." (PMID 38700812, 2024). "Based on these studies, we hypothesized that the activation of the IDO-related Kyn pathway in the PrL and IL might underlie depression-like behavior in ICV-STZ rats." (PMID 39000602, 2024). "Similarly, PRL-deficient patients with panhypopituitarism showed higher depression scores compared to healthy controls, and lower sexual function scores in males." (PMID 39172174, 2024). "Increased PRL among subjects in the depression group could indicate reduced inhibition of PRL secretion by central dopamine, suggesting an underlying pathophysiology of diminished dopamine neurotransmission as a cause of the depression symptoms." (PMID 37895130, 2023). "Prolactin may be also associated with the occurrence of psychopathological disorders, including depression, therefore another important research direction should include the analysis of this issue in the context of the observed cognitive disorders." (PMID 36581642, 2022). "Altogether, these results suggest that the density of PNNs in the PrL is associated with depressive-like behaviors in young-aged rats, and it may serve as a potential endophenotype or therapeutic target for depression." (PMID 32116542, 2020). "Further, it has been found that prolactin, thyroid hormone, catecholamine, arginine vasopressin, adrenocorticotropin and cortisol are all proposed to be suicide risk in patients with depression levels are associated with suicide attempts in patients with a history of suicidal behavior." (PMID 32398015, 2020).